DNAJC17 (DnaJ heat shock protein family (Hsp40) member C17)
Description:
May negatively affect PAX8-induced thyroglobulin/TG transcription.
Synonyms: FLJ10634
Tractability: PROTAC: ubiquitination databases record sites on it; its protein half-life has been measured.
Gene: Protein-coding gene on chromosome 15 (40,765,161 to 40,807,498, reverse strand). Ensembl gene ENSG00000104129.
Subcellular location: Cytoplasm; Nucleus
Subcellular location (Human Protein Atlas): Nucleoplasm
Gene Ontology:
Molecular function: protein binding; nucleic acid binding; RNA binding
Biological process: spliceosomal complex disassembly
Cellular component: cytoplasm; nucleus; spliceosomal complex
Genetic constraint (gnomAD): Loss-of-function variants: 36 observed, 50.04 expected, observed/expected ratio (o/e) 0.72, 90% interval 0.55 to 0.95. The upper end of that interval is the gene's LOEUF score, 0.95, which puts it in group 4 of 6, group 1 being the genes least tolerant of losing a copy. Missense variants: 355 observed, 390.34 expected, observed/expected ratio (o/e) 0.91, 90% interval 0.83 to 0.99. Synonymous variants: 117 observed, 150.7 expected, observed/expected ratio (o/e) 0.78, 90% interval 0.67 to 0.9.
Homologues: Orthologues: chimpanzee DNAJC17 (99% identical), guinea pig Dnajc17 (90% identical), rabbit DNAJC17 (90% identical), dog DNAJC17 (90% identical), macaque DNAJC17 (88% identical), mouse Dnajc17 (88% identical), pig DNAJC17 (81% identical), rat Dnajc17 (80% identical), tropical clawed frog dnajc17 (69% identical), zebrafish dnajc17 (64% identical), Drosophila melanogaster CG17187 (46% identical), Caenorhabditis elegans dnj-2 (13% identical), and 3 more. Paralogues in human: DNAJC13 (31% identical), DNAJC14 (23% identical), DNAJC21 (21% identical), DNAJC10 (21% identical), DNAJC1 (20% identical), DNAJC16 (20% identical), DNAJC11 (20% identical), DNAJC2 (19% identical), DNAJC7 (18% identical), DNAJC25 (16% identical), DNAJC3 (15% identical), DNAJC5 (15% identical), and 8 more.
Diseases named in the same sentence as DNAJC17 in open-access papers:
DNAJC17 is named in the same sentence as 9 diseases in open-access papers, as found by Europe PMC text mining. Sharing a sentence is not in itself a finding about the gene and the disease. The quoted sentences say what the papers report.
osteosarcoma (2 papers, 2022 to 2024). A usually aggressive malignant bone-forming mesenchymal neoplasm, predominantly affecting adolescents and young adults. "However, high expression of DNAJC17 is a favorable prognostic factor in patients with osteosarcoma." (PMID 35962451, 2022). "Among the four pivotal HSPs, Kaplan-Meier curves revealed that osteosarcoma patients with high expression levels of DNAJC5B and DNAJC17 exhibited longer OS, though the differences were not statistically significant." (PMID 39430254, 2024).
retinitis pigmentosa (2 papers, 2018 to 2021). Retinitis pigmentosa (RP) is an inherited retinal dystrophy leading to progressive loss of the photoreceptors and retinal pigment epithelium and resulting in blindness usually after several decades. "Mutations in the DNAJC17 gene have been reported to be associated with retinitis pigmentosa and hypogammaglobulinemia." (PMID 33747556, 2021).
bovine tuberculosis (1 paper, 2024). "Other genes found in the present study related to immunity and adaptation in literature were DNAJC17 (heat tolerance in Zebu cattle), GCHFR, MDGA2 (heat stress in cows), FOXF1, NKG7 (bovine tuberculosis response), and SIGLEC10." (PMID 39766784, 2024).
congenital hypothyroidism (1 paper, 2018). A thyroid hormone deficiency present from birth. "DNAJC17 is a heat shock protein (HSP40) family member, identified in mouse as susceptibility gene for congenital hypothyroidism." (PMID 29773831, 2018).
COVID-19 (1 paper, 2025). A disease caused by infection with severe acute respiratory syndrome coronavirus 2. "Our analysis revealed increased plasma levels of DNAJC9, DNAJC17, and DNAJA4 in PLWH diagnosed with COVID-19, though these elevations were not statistically significant after FDR adjustment." (PMID 40568587, 2025).
myeloproliferative disorder (1 paper, 2018). A clonal hematopoietic stem cell disorder, characterized by proliferation in the bone marrow of one or more of the myeloid (i.e., granulocytic, erythroid, megakaryocytic, and mast cell) lineages. "In humans, germline homozygous mutations in DNAJC17 have been found in syndromic retinal dystrophy patients, while heterozygous mutations represent candidate pathogenic events for myeloproliferative disorders." (PMID 29773831, 2018).
cancer (2 papers, 2016 to 2022). A tumor composed of atypical neoplastic, often pleomorphic cells that invade other tissues. "The GSCA database was exploited to analyze the relationship between the drug sensitivity and the expression of LARS and DNAJC17 based on the data from the Cancer Drug Sensitivity Genomics Database (GDSC)." (PMID 35962451, 2022).
DNAJC17 also shares sentences with these, for which no sentence is quoted: infection (1 paper); Retinal dystrophy (1).